BCCIP (BRCA2 and CDKN1A interacting protein)
Description:
During interphase, required for microtubule organizing and anchoring activities. During mitosis, required for the organization and stabilization of the spindle pole. Isoform 2/alpha is particularly important for the regulation of microtubule anchoring, microtubule stability, spindle architecture and spindle orientation, compared to isoform 1/beta. May promote cell cycle arrest by enhancing the inhibition of CDK2 activity by CDKN1A. May be required for repair of DNA damage by homologous recombination in conjunction with BRCA2. May not be involved in non-homologous end joining (NHEJ).
Synonyms: TOK1; BCCIPalpha; TOK-1
Tractability: PROTAC: ubiquitination databases record sites on it; its protein half-life has been measured.
Gene: Protein-coding gene on chromosome 10 (125,823,525 to 125,853,695, forward strand). Ensembl gene ENSG00000107949.
Subcellular location: Nucleus; Cytoplasm, cytoskeleton, microtubule organizing center, centrosome, centriole; Cytoplasm, cytoskeleton, spindle pole; Cytoplasm, cytoskeleton, microtubule organizing center, centrosome (Isoform 1); Cytoplasm, cytoskeleton, microtubule organizing center, centrosome (Isoform 2)
Subcellular location (Human Protein Atlas): Nucleoplasm; Cytosol
Gene Ontology:
Molecular function: DNA binding; identical protein binding; kinase regulator activity; protein binding; RNA binding
Biological process: microtubule anchoring; microtubule cytoskeleton organization; mitotic spindle assembly; mitotic spindle organization; neuroendocrine cell differentiation; regulation of cyclin-dependent protein serine/threonine kinase activity; DNA damage response
Cellular component: centriole; centrosome; mitotic spindle pole; nuclear cyclin-dependent protein kinase holoenzyme complex; nucleoplasm; nucleus; spindle pole
Genetic constraint (gnomAD): Loss-of-function variants: 22 observed, 29.82 expected, observed/expected ratio (o/e) 0.74, 90% interval 0.53 to 1.05. The upper end of that interval is the gene's LOEUF score, 1.05, which puts it in group 4 of 6, group 1 being the genes least tolerant of losing a copy. Missense variants: 325 observed, 334.15 expected, observed/expected ratio (o/e) 0.97, 90% interval 0.89 to 1.07. Synonymous variants: 123 observed, 124.19 expected, observed/expected ratio (o/e) 0.99, 90% interval 0.86 to 1.15.
Homologues: Orthologues: guinea pig BCCIP (83% identical), dog BCCIP (82% identical), mouse Bccip (79% identical), rat Bccip (78% identical), pig BCCIP (77% identical), tropical clawed frog bccip (68% identical), zebrafish bccip (53% identical), Drosophila melanogaster CG9286 (31% identical), Caenorhabditis elegans ZK1127.4 (24% identical).
Diseases named in the same sentence as BCCIP in open-access papers:
BCCIP is named in the same sentence as 36 diseases in open-access papers, as found by Europe PMC text mining. Sharing a sentence is not in itself a finding about the gene and the disease. The quoted sentences say what the papers report.
colorectal cancer (4 papers, 2016 to 2025). A primary or metastatic malignant neoplasm that affects the colon or rectum. "Dysregulation of BCCIP is associated with hepatocellular carcinoma, colorectal cancer tissue and renal cell carcinoma tissue." (PMID 37981907, 2023). "Low expression of BCCIP had been observed in various primary tumor tissues with clinical diagnoses, including OC, renal cell carcinoma, and colorectal cancer." (PMID 39932052, 2025). "Downregulation of BCCIP expression has been reported in brain cancer, laryngeal cancer, ovarian cancer, renal cell carcinoma, colorectal cancer, and recently among hepatocellular carcinoma." (PMID 29047390, 2017). "Although the low expression of BCCIP is observed in multiple clinically diagnosed primary tumor tissues such as ovarian cancer, renal cell carcinoma and colorectal carcinoma, the mechanism of how BCCIP is regulated in cells is still unclear." (PMID 27535137, 2016). "Recently, other colleagues and we have reported that BCCIP was down-regulated in several cancer tissues such as renal cell carcinoma, ovarian cancer and colorectal carcinoma." (PMID 27535137, 2016).
lung adenocarcinoma (4 papers, 2023 to 2025). A carcinoma that arises from the lung and is characterized by the presence of malignant glandular epithelial cells. "Overexpression of BCCIP is associated with shorter survival time of patients with lung adenocarcinoma, and in vitro experiments showed that interference of BCCIP inhibits the proliferation of lung adenocarcinoma and blocks in G1/S phase." (PMID 38077434, 2023). "Elevated BCCIP expression levels are correlated to a prognosis of poorer overall patient survival in lung adenocarcinoma and esophageal squamous cell carcinoma." (PMID 37981907, 2023).
colon cancer (2 papers, 2016 to 2019). "Based on UCSC database (ChIP-Seq) search, we found that YY1 was restricted to the BCCIP transcriptional start site proximal region in different types of cell lines including human lung carcinoma type II epithelium-like A549, human liver hepatocellular carcinoma HepG2 and human colon cancer HCT116." (PMID 27535137, 2016).
laryngeal carcinoma (2 papers, 2009 to 2017). Carcinoma that arises from the laryngeal epithelium.
microcephaly (2 papers, 2012 to 2017). A congenital or acquired developmental disorder in which the circumference of the head is smaller than normal for the person's age and sex. "In this study, we found that BCCIP deficiency causes proliferation arrest among progenitor cells, leading to severe neurogenesis defects, including: microcephaly, ataxia, cerebral and cerebellar development disorders, and growth retardation." (PMID 22292003, 2012). "BCCIP deficiency impaired embryonic and postnatal neural development, causing severe ataxia, cerebral and cerebellar defects, and microcephaly." (PMID 22292003, 2012). "An intriguing observation is that while the severe ataxia phenotype among the BCCIP deficient mice gradually improved when the mice grow into adults, we observed consistent microcephaly throughout the life span, and the majority of adult BCCIP deficient mice failed balance beam test." (PMID 22292003, 2012). "The Nbs1Nestin-Cre conditional knockout mice had severe neural degeneration, ataxia, and microcephaly, to a similar extent as our BCCIP-CKD mice." (PMID 22292003, 2012). "Interestingly, in an independent transgenic line (LoxPshBCCIP+/+-13) that has a lower BCCIP knockdown efficiency than the LoxPshBCCIP+/+-4 used in this report, a milder microcephaly phenotype can be observed." (PMID 22292003, 2012).
ovarian carcinoma (2 papers, 2016 to 2017). A malignant neoplasm originating from the surface ovarian epithelium. "Despite a role of BCCIP in genomic stability, germline mutations in the gene are rare in breast and ovarian cancer families, and BCCIP expression status in sporadic breast cancer has not been examined." (PMID 29047390, 2017). "However, BCCIP mutation is rare in cancers based on a search of the TCGA database, BCCIP germline mutations are absent in breast and ovarian cancer families, and the BCCIP expression status in sporadic breast cancer tissues has not been examined." (PMID 29047390, 2017).
astrocytic tumor (1 paper, 2009). A glial tumor of the brain or spinal cord showing astrocytic differentiation. "The BCCIP protein expression in 96 cases of grade II–IV astrocytic tumors was detected by immunohistochemistry (IHC)." (PMID 19653894, 2009). "Furthermore, the frequency of lacking BCCIP expression is associated with the aggressiveness of astrocytic tumors." (PMID 19653894, 2009). "Because majority of the tumor on the slides are astrocytoma, and most astrocytic tumor cells express the unique marker glial fibrillary acid protein (GFAP), we first checked if BCCIP is expressed in normal GFAP positive cells." (PMID 19653894, 2009). "However, BCCIP protein expression was not detectable in ~45% of all astrocytic tumors, and in > 60% in the grade IV glioblastoma." (PMID 19653894, 2009).
astrocytomas (1 paper, 2009). "We found that BCCIP expression is down-regulated in a significant portion of astrocytomas, and the loss of BCCIP expression is more frequent in the aggressive form of astrocytomas." (PMID 19653894, 2009). "Given that BCCIP is involved in important processes relevant to the maintenance of genome stability and its localization at 10q26, we investigated the possibility of BCCIP alterations in more than 100 cases of astrocytomas." (PMID 19653894, 2009). "Here we show that a significant portion of astrocytomas has down-regulation of BCCIP." (PMID 19653894, 2009). "Furthermore, BCCIP down-regulation is correlated with the aggressiveness of astrocytomas." (PMID 19653894, 2009). "In this study, we investigated whether BCCIP is altered in astrocytomas." (PMID 19653894, 2009). "The correlation of lacking BCCIP expression with the WHO grade is consistent with the association between 10q26 abnormalities and the poor prognosis of astrocytomas." (PMID 19653894, 2009). "Our data implicate a role of BCCIP in astrocytic tumorigenesis, and lack of BCCIP may be used as a marker for astrocytomas." (PMID 19653894, 2009). "The human BCCIP gene is located at 10q26.1, and a recent report suggested that BCCIP may be absent in at least one astrocytoma cell line." (PMID 19653894, 2009). "Three of the five GFAP negative astrocytomas are also BCCIP negative." (PMID 19653894, 2009). "Among 91 cases of GFAP positive astrocytomas, 40 were BCCIP negative, an overall rate of 44.8%." (PMID 19653894, 2009). "Interestingly, we found that 5 out of 26 cases (19.2%) WHO grade II astrocytomas are BCCIP negative, whereas 13/29 (44.8%) WHO grade III and 25/41 (60.1%) WHO grade IV astrocytomas are BCCIP negative." (PMID 19653894, 2009).
Ataxia (1 paper, 2012). Ataxia refers to impaired coordination of voluntary muscle movement. "Coincidental with the relief of ataxia symptom around age p28, the BCCIP-CKD mice began to gain weight." (PMID 22292003, 2012). "In addition, severe ataxia was not reported in the BRCA2 deficient mice, while BCCIP-CKD mice displayed severe ataxia." (PMID 22292003, 2012). "About 60% BCCIP-CKD mice had severe ataxia, and could not pass the balance beam test at age P21." (PMID 22292003, 2012).
Bloom syndrome (1 paper, 2011). Bloom syndrome (BSyn) is a rare chromosomal breakage syndrome characterized by a marked genetic instability associated with pre- and postnatal growth retardation, facial sun-sensitive telangiectatic erythema, increased susceptibility to infections, and predisposition to cancer. "We further measured whether BCCIP deficiency causes increased sister chromatid exchange (SCE), which is seen in Bloom syndrome and several genetic disorder related to replication stress." (PMID 21966279, 2011).
brain tumor (1 paper, 2009). "To confirm the loss of BCCIP, we measured the BCCIP protein expression in brain tumor tissue sections." (PMID 19653894, 2009). "Because BCCIP has also been shown to be required for completion of mitosis, and severe knockdown of BCCIP resulted in growth retardation in other cell types, it remains to be addressed how loss of BCCIP expression may lead to brain tumor survival." (PMID 19653894, 2009). "However, additional investigation, preferably with animal knock-out or knock-down models, is needed to conclude whether BCCIP defects directly cause brain tumor." (PMID 19653894, 2009). "Therefore, we were interested in determining whether altered BCCIP is associated with brain tumors." (PMID 19653894, 2009). "The BCCIP gene is located at chromosome 10q26.2, a region frequently altered in brain tumors." (PMID 19653894, 2009). "We found that BCCIP is down-regulated in a major portion of these brain tumors." (PMID 19653894, 2009).
breast carcinoma (1 paper, 2017). "Our data suggest a confounding role of BCCIP deficiency in modulating breast cancer development by enhancing tumor initiation but hindering progression." (PMID 29047390, 2017). "We further constructed a unique BCCIP knockdown mouse model to determine whether a partial BCCIP deficiency leads to spontaneous breast cancer formation." (PMID 29047390, 2017). "The aims of this study were to determine whether BCCIP deficiency contributes to mammary tumorigenesis, especially for a subset of breast cancers with 53BP1 abnormality, and to reveal the mechanistic implications of BCCIP in breast cancer interventions." (PMID 29047390, 2017). "In this study, we surveyed the BCCIP protein level in breast cancer tissues, and generated a transgenic mouse model to conditionally knockdown BCCIP expression in the mouse mammary gland epithelium to evaluate the effects of BCCIP deficiency in mammary tumorigenesis." (PMID 29047390, 2017). "Interestingly, we found that all three cases had lost 53BP1 expression, which is consistent with the observed codownregulation of BCCIP and 53BP1 in human breast cancer." (PMID 29047390, 2017). "Our study shows that a significant fraction of human breast cancers has reduced BCCIP expression." (PMID 29047390, 2017). "However, in the breast cancers that evolved from the benign lesions of BCCIP-CKD mice, BCCIP levels remained reduced, suggesting that an alternative genetic change(s) may have occurred to bypass the dependence on BCCIP for tumor progression." (PMID 29047390, 2017).
endometriosis (1 paper, 2025). The growth of functional endometrial tissue in anatomic sites outside the uterine body. "We additionally found a downregulation of BCCIP expression in peritoneal lesions of endometriosis patients compared to healthy endometrium." (PMID 40135061, 2025). "Moreover, a significant downregulation of several potential targets, including CDK6, BCCIP, PTEN, TCF7L1, TCF7L2, ROBO1, COL4A2, E‐Cadherin, and N‐Cadherin, was observed in the transfected cells and endometriosis patients." (PMID 40135061, 2025).
ependymoma (1 paper, 2009). A WHO grade II, slow growing tumor of children and young adults, usually located intraventricularly. "In addition, 2 out 6 GFAP positive oligodendroglioma are BCCIP negative, and all 5 cases of ependymomas are GFAP negative but BCCIP positive." (PMID 19653894, 2009).
Epidermal Inclusion Cyst (1 paper, 2017). Epidermal inclusion cyst (EIC), also known as sebaceous cyst and epidermoid cyst, is the most common cyst of the skin. "In a K14-Cre-mediated conditional BCCIP knockdown mouse model, we found that BCCIP downregulation causes a formation of benign modules in the mammary glands, resembling the epidermal inclusion cyst of the breast." (PMID 29047390, 2017).
glioblastoma (1 paper, 2009). The most malignant astrocytic tumor (WHO grade IV). "We found that 20 out of 45 cases of glioblastoma DNA have significant loss of BCCIP with p < 0.01, an overall rate of 44.5%." (PMID 19653894, 2009). "Nevertheless, our data indicate that BCCIP gene loss or alteration is common in glioblastomas." (PMID 19653894, 2009). "Thus a total of ~75% glioblastomas have BCCIP loss (p < 0.05)." (PMID 19653894, 2009). "We first estimated the BCCIP gene copy numbers in genomic DNA from 45 cases of glioblastomas (grade IV)." (PMID 19653894, 2009). "About 45% glioblastoma have significant (p < 0.01) reduction of BCCIP gene copy number when compared to normal DNA." (PMID 19653894, 2009).
kidney tumors (1 paper, 2009). "DHX32 was reported as anti-sense to another gene, BCCIP (BRCA2 and CDKN1A Interacting Protein), and BCCIP was down-regulated in kidney tumors." (PMID 19161603, 2009).
mammary tumor (1 paper, 2017). "The increased frequency of latent benign nodules and the reduced incidence of de-novo malignant mammary tumors in the BCCIP-CKD group suggest that BCCIP downregulation may promote the initiation of mammary tumor formation but prohibit the de-novo tumor progression." (PMID 29047390, 2017).